NECAB1 (N-terminal EF-hand calcium binding protein 1)
Synonyms: EFCAB1; EFCBP1; STIP-1
Tractability: PROTAC: its protein half-life has been measured.
Gene: Protein-coding gene on chromosome 8 (90,791,741 to 90,959,393, forward strand). Ensembl gene ENSG00000123119.
Subcellular location: Cytoplasm
Subcellular location (Human Protein Atlas): Nucleoplasm; Cytosol; Mitotic spindle; Primary cilium; Primary cilium tip
Gene Ontology:
Molecular function: identical protein binding; protein binding; calcium ion binding
Biological process: regulation of amyloid precursor protein biosynthetic process
Cellular component: cytosol; nucleoplasm; cytoplasm
Genetic constraint (gnomAD): Loss-of-function variants: 16 observed, 20.97 expected, observed/expected ratio (o/e) 0.76, 90% interval 0.52 to 1.16. The upper end of that interval is the gene's LOEUF score, 1.16, which puts it in group 5 of 6, group 1 being the genes least tolerant of losing a copy. Missense variants: 207 observed, 191.05 expected, observed/expected ratio (o/e) 1.08, 90% interval 0.97 to 1.22. Synonymous variants: 84 observed, 73.81 expected, observed/expected ratio (o/e) 1.14, 90% interval 0.95 to 1.37.
Homologues: Orthologues: chimpanzee NECAB1 (100% identical), macaque NECAB1 (99% identical), rabbit NECAB1 (98% identical), mouse Necab1 (97% identical), guinea pig NECAB1 (95% identical), dog NECAB1 (95% identical), rat Necab1 (89% identical), pig NECAB1 (86% identical), tropical clawed frog necab1 (79% identical), zebrafish necab1 (74% identical). Paralogues in human: NECAB3 (47% identical), NECAB2 (41% identical).
Diseases named in the same sentence as NECAB1 in open-access papers:
NECAB1 is named in the same sentence as 13 diseases in open-access papers, as found by Europe PMC text mining. Sharing a sentence is not in itself a finding about the gene and the disease. The quoted sentences say what the papers report.
autism (2 papers, 2021 to 2022). Persistent deficits in social interaction and communication and interaction as well as a markedly restricted repertoire of activity and interest as well as repetitive patterns of behavior. "Meanwhile, missense mutations in NECAB1 are associated with developmental language disorders, one of the frequent comorbidities in autism." (PMID 35909444, 2022).
Cushing syndrome (1 paper, 2023). Cushing's syndrome (CS) encompasses a group of hormonal disorders caused by prolonged and high exposure levels to glucocorticoids that can be of either endogenous (adrenal cortex production) or exogenous (iatrogenic) origin. "While insulin secretion was enhanced in typical cases of Cushing's syndrome and steroid-induced diabetes, it is plausible to speculate that GR-regulated NECAB1 expression in β-cells may have a pathophysiological role in diabetes development in some stages of the disease." (PMID 37863964, 2023).
diabetes mellitus (1 paper, 2023). A metabolic disorder characterized by abnormally high blood sugar levels due to diminished production of insulin or insulin resistance/desensitization. "More detailed analysis, using genetically modified mice, is necessary to elucidate the precise role of NECAB1 in pancreatic islets in the normal state or development of diabetes mellitus." (PMID 37863964, 2023). "NECAB1 has been shown to be elevated in islets in pathological conditions such as diabetes and obesity." (PMID 37863964, 2023). "Future studies may prove targeting GR and/or NECAB1 in β-cells as a novel therapeutic approach for obesity-related diabetes mellitus, which has become a worldwide pandemic." (PMID 37863964, 2023). "NECAB1 may play a novel role in the adipoinsular axis and could be potentially involved in the pathophysiology of obesity-related diabetes mellitus." (PMID 37863964, 2023). "In conclusion, we identified NECAB1 as a negative regulator of insulin secretion, and induction of NECAB1via GR activation may mediate pancreatic β-cell dysfunction in some contexts such as obesity-related diabetes mellitus." (PMID 37863964, 2023).
epilepsy (1 paper, 2025). A brain disorder characterized by episodes of abnormally increased neuronal discharge resulting in transient episodes of sensory or motor neurological dysfunction, or psychic dysfunction. "While parvalbumin and calretinin are well-characterized CaBPs, N-Terminal EF-Hand Calcium-Binding Protein 1 (NECAB1) remains understudied in epilepsy, despite its association with neurodegenerative conditions." (PMID 40430045, 2025). "Furthermore, NECAB1 has been listed among potential epilepsy-associated genes." (PMID 40430045, 2025). "In the chronic phase of KA-induced epilepsy, NECAB1 expression was significantly upregulated in the PVT and bilaterally in the amygdala." (PMID 40430045, 2025). "In this study, we demonstrated that while epilepsy increased the density of NECAB1-positive cells, animals treated with either levetiracetam or brivaracetam exhibited cell densities comparable to those observed in the sham-operated control group." (PMID 40430045, 2025). "In our study, in the chronic phase of KA-induced epilepsy, we observed an increase in NECAB1 expression in several brain regions, namely the endopiriform nucleus, the amygdala, and the paraventricular nucleus of the thalamus." (PMID 40430045, 2025). "Understanding NECAB1’s role in epilepsy and neurodegeneration could open new therapeutic avenues targeting calcium-binding proteins for neuronal stability and excitability regulation." (PMID 40430045, 2025).
pulmonary fibrosis (1 paper, 2022). Chronic progressive interstitial lung disorder characterized by the replacement of the lung tissue by connective tissue, leading to progressive dyspnea, respiratory failure, or right heart failure. "In addition, no other potential markers IGFL2, NECAB1, SCG5 were found to play a role in pulmonary fibrosis." (PMID 36507532, 2022).
Sepsis (1 paper, 2020). Sepsis is defined as life-threatening organ dysfunction caused by a dysregulated host response to infection. "In adult sepsis there is indirect interaction between GPR84, CD177, and TDRD9 through EXOSC4 and with CD177 through NECAB1." (PMID 32318053, 2020). "In adult sepsis, genes TDRD9, GPR84, and CD177 interacted via overlapped genes EXOSC4 (TDRD9 ↔ GPR84 ↔ CD177), ZDHHC19 (TDRD9 ↔ CD177) and NECAB1 (GPR84 ↔ CD177)." (PMID 32318053, 2020).
cancer (1 paper, 2016). A tumor composed of atypical neoplastic, often pleomorphic cells that invade other tissues. "Using RT-PCR, we found NECAB2 and NECAB3, but not NECAB1, to be expressed in cancer cells." (PMID 26948053, 2016).
NECAB1 also shares sentences with these, for which no sentence is quoted: Obesity (1 paper); psychiatric disorder (1); status epilepticus (1); Stroke (1); temporal lobe epilepsy (1); tumor (1).